INS (insulin)
Diseases named in the same sentence as INS in open-access papers (continued):
Sharing a sentence is not in itself a finding about the gene and the disease.
type 2 diabetes (continued). "Impaired insulin metabolism, hypertension, weight gain, and changes in serum lipids in patients receiving MMTPs may lead to long-term side effects, metabolic abnormalities, infections, chronic obstructive pulmonary disease, type 2 diabetes, and higher mortality." (PMID 35685534, 2022). "Generally, as in type 2 diabetes patients, KPD patients have been demonstrated to have reduced insulin secretory capacity compared to healthy matched controls even during remission." (PMID 35462815, 2022). "In the present study, we reassessed the characteristics of Japanese outpatients with type 2 diabetes requiring insulin therapy by measuring the C‐CPI and UCPCR to identify the requirement for insulin therapy." (PMID 35229479, 2022). "Overall, type 2 diabetes, uterine fibroids, higher BMI, higher PAI-1, higher fasting insulin, early insulin secretion, longer telomere length, higher testosterone and higher plasma cortisol levels are associated with increased risk of EC." (PMID 35615721, 2022). "Scores similar to 31.3% in an Algerian study on type 2 diabetics (on ADO and/or insulin), 33.1% in an Ethiopian study of a similar size population, but lower than 88.1% in a Pakistani study of type 1 diabetics on insulin were published." (PMID 35573427, 2022). "In SGLT2-treated type 2 diabetic patients with euglycemic DKA, there is a lower insulin-to-glucagon ratio due to this increased glucosuria which stimulates lipolysis." (PMID 35251838, 2022). "Although targeted in extrapancreatic tissues by several drugs used to treat type 2 diabetes, the role of AMP-activated protein kinase (AMPK) in the control of insulin secretion is still debatable." (PMID 35294578, 2022). "Thus, understanding the effects of different AAs on insulin release and kinetics under different metabolic conditions may help to gain further insight on the development of several diseases, including type 2 diabetes, and to develop therapeutic strategies based on appropriate dietary regimen." (PMID 36187117, 2022). "Moreover, a single supplement of dried Pleurotus ostreatus (P. ostreatus, 50 mg/kg BW) 30 min before intake of 75 g pure glucose lowered 2 h PBG in patients with type 2 diabetes mellitus (T2DM), probably due to increased insulin release." (PMID 34505919, 2022). "However, there is increasing support for the theory that hyperinsulinaemia may be the distinct first event in the pathogenesis of type 2 diabetes, with the primary hyperinsulinaemic factors being posited as hypersecretion of insulin from the beta cells and/or reduced hepatic insulin clearance." (PMID 36166072, 2022). "The present study compared palmatine to metformin and glimepiride in a type 2 diabetes model on ADME analysis and insulin resistance via the PI3K/AKT/GLUT4 signaling pathway: in vitro, in vivo, ex vivo, and in silico molecular docking." (PMID 36355489, 2022). "They reported that lower insulin clearance, measured by MCR (or MCRI, as used by Shah) during euglycemic clamps, was predictive of type 2 diabetes." (PMID 35163746, 2022). "Hence, the aim of the trial is to explore the effect of telemonitoring in patients with type 2 diabetes (T2D) on insulin therapy." (PMID 36476605, 2022). "As a useful prescription for type 2 diabetes, the action of DPP-4 is based on inhibiting the degradation of type 1 glucagon-like peptide (GLP-1), an incretin stimulates the glucose-dependent insulin secretion of β cells." (PMID 35290413, 2022). "The metabolic symptoms are dyslipidemia, hypertension, cardiovascular diseases, hepatic steatosis, type-2 diabetes (T2DM), impaired glucose tolerance (IGT), and increased resistance to insulin." (PMID 35886014, 2022). "In the treatment of type-2 diabetes, FFA4 ligands have attracted considerable interest because of their ability to enhance glucose-dependent insulin production from pancreatic β-cells as well as their anti-inflammatory actions in adipocytes and the gut." (PMID 36293091, 2022).
type 2 diabetes (continued). "In a randomized, double-blind controlled clinical trial performed on 30 type-2 diabetic cases, daily consumption of 10 g of purslane seed powder combined with regular care and exercise could significantly reduce fasting and post-prandial serum levels of blood glucose and insulin." (PMID 36474567, 2022). "A total of 43 pregnancies were enrolled in this study, including 14 normal pregnancies (Control), 10 diet-controlled GDM (GDM1), 9 insulin-controlled GDM (GDM2), and 10 PGDM (Type 2 diabetes)." (PMID 35955706, 2022). "The difference between the two diabetic models is that, in type 2 diabetes, hyperglycemia occurs first and then oxidative stress, but in the STZ diabetic model, oxidative stress occurs first and then insulin depletion and hyperglycemia." (PMID 36109786, 2022). "Analysis using the Enrichr tool showed that genes downregulated by iAsIII treatment are enriched in maturity onset diabetes of the young (MODY), T2D, insulin secretion, and calcium signaling pathways, as well as MAPK signaling and cell cycle." (PMID 35314868, 2022). "PGZ, a type of thiazolidinedione, improves insulin sensitivity and lipid metabolism through the activation of PPAR-γ; thus, PGZ has been used widely to normalize glucose levels in patients with type 2 diabetes." (PMID 36613856, 2022). "Expression of fusion proteins is reduced in the islets of patients with type II diabetes, indicating that SNARE‐mediated fusion defect is closely related to insulin‐based metabolic diseases." (PMID 36111501, 2022). "Aerobic exercise training increases cardiac output, oxidative enzymes, and insulin sensitivity in patients with T2DM, e.g., regular training reduced A1C, insulin resistance, and triglycerides in patients with type 2 diabetes." (PMID 35463021, 2022). "Type 2 diabetes mellitus (T2DM) is a metabolic disease characterized by long-term hyperglycemia, insulin resistance, and a relative lack of insulin, which increases the risk for cognitive impairment." (PMID 35517056, 2022). "Therefore, an alternative explanation for the progression of type 2 diabetes is that impaired insulin secretion is a corollary to the progression of obesity, thus, triggering a cascade leading to islet cell destruction and the long-term complications of type 2 diabetes." (PMID 35163806, 2022). "In type 2 diabetes, miR-342-3p is predicted to inhibit GLUT2 and trigger impaired insulin secretion in pancreatic β islet cells." (PMID 36704034, 2022). "Vanadium-based insulin mimetic compounds are known PTP1B inhibitors, and few were/are in clinical trials for the treatment of type 2 diabetes and obesity." (PMID 35159385, 2022). "For instance, it was shown that when type 2 diabetes db/db mice were treated with the GLP-1 receptor activator, liraglutide for 2 weeks, insulin biosynthesis and glucose-stimulated insulin secretion were increased." (PMID 35453568, 2022). "The RNA-seq data show that the type 2 diabetes, PPAR pathway and insulin signaling are enriched in KOIEC tissue, which is in accordance with our previous reports that adipocyte specific Cul4b knockout mice are susceptible to obesity." (PMID 35197566, 2022). "Proinflammatory cytokines act via a paracrine-dependent mechanism to impair hepatic metabolism and insulin action in the liver, contributing to NAFL in obesity and type 2 diabetes." (PMID 35700043, 2022). "Research on blood sugar regulation of type 2 diabetes by CSE found that CSE can reduce colonic mucosal damage, increase serum insulin levels and increase HLDL levels to control blood sugar." (PMID 35923203, 2022). "Due to its biological effects, pioglitazone is widely used as a type 2 diabetes (T2D) treatment, and several studies have shown that PPAR-γ activation can be directly correlated with insulin sensibilization and the regulation of lipidic metabolism." (PMID 35741327, 2022).
type 2 diabetes (continued). "The lack of insulin action on the exocrine pancreas, leading in tissue atrophy, as insulin is a potent growth factor for the exocrine pancreas (disruption of the endocrine and exocrine connection), could explain the reduction in pancreas size in both type 1 and type 2 diabetes patients." (PMID 35326092, 2022). "Type 2 diabetes mellitus (T2DM) is a public health problem of considerable magnitude that is characterized by hyperglycemia, insulin resistance, and gradual exhaustion of insulin secretion from pancreatic β cells." (PMID 35872977, 2022). "Type 2 diabetes (T2DM) is distinguished by a decreased sensibility to insulin." (PMID 35808386, 2022). "The fasting glucose, free insulin and HOMA-IR values were significantly elevated in patients, and results confirmed the concurrent diagnosis of the PCOS patients with type 2 diabetes." (PMID 35270805, 2022). "Type 2 diabetes mellitus (T2DM) is a progressive metabolic disease characterized by pancreatic β-cell dysfunction and peripheral insulin resistance, leading to defects in glucose metabolism and chronic low-grade inflammation." (PMID 35242721, 2022). "Except for fasting insulin, which was found to be a cause but not a consequence of liability to type 2 diabetes, these traits were deemed to have bidirectional relationships with liability to type 2 diabetes when interpreted using the arbitrary 5% FDR threshold selected for this study." (PMID 35129650, 2022). "Postpartum insulin use was required in 85 women with DIP, including 12 women with GDM A2, 14 women with type I diabetes, and 59 women with type 2 diabetes." (PMID 35585514, 2022). "Previously, Inonotus obliquus has been shown to enhance glucose tolerance and insulin sensitivity in T2DM mice and improve hyperglycemic symptoms in type 2 diabetes patients." (PMID 36686454, 2022). "Besides its antioxidant and anti-inflammatory activities, coffee exerts specific effects that improve glucose and insulin status and is well recognized for preventing and treating type 2 diabetes mellitus (T2DM)." (PMID 35496060, 2022). "This study was conducted on subjects with impaired fasting glucose and early type 2 diabetes, and it was expected that OSM would lower the blood glucose level and reduce insulin secretion." (PMID 35956334, 2022). "Metformin reduced thyroid volume in patients with type 2 diabetes, likely due to direct inhibition of thyroid growth by activation of the AMPK/ mTOR pathway and antagonizing the growth-stimulatory effect of insulin by inhibition of the MAPK pathway." (PMID 35158824, 2022). "Type 2 diabetes mellitus, T2DM, is a metabolic syndrome characterized by chronic hyperglycemia due to defects in the activity and insulin release." (PMID 36362563, 2022). "Data which are available are based upon insulin levels which are observed during the euglycemic clamp procedure—the so-called “metabolic clearance rate” of insulin (MCR) is decreased in obesity, IGT, and type 2 diabetes." (PMID 35163746, 2022). "Type 2 diabetes mellitus (T2DM) is a complex metabolic disorder characterized by increased IR in the liver, skeletal muscle, and adipose tissue, along with impaired insulin secretion by pancreatic β-cells, particularly in response to a glucose stimulus." (PMID 35645292, 2022). "Some of current medications for type 2 diabetes mellitus, such as metformin, glimepiride, glucagon-like peptide-1 (GLP-1), and insulin, possibly played beneficial roles in bone metabolism." (PMID 36589840, 2022). "In obesity, insulin resistance of AT is one major factor contributing to unbalanced insulin response, and furthermore in type 2 diabetes mellitus (T2DM), AT becomes a sink of glucose: Increasing fat mass can compensate for reduced glucose uptake per mass of AT." (PMID 35363252, 2022).
type 2 diabetes (continued). "Type 2 diabetes mellitus (T2DM) is a chroniccondition characterizedby the dysregulation of carbohydrate, lipid, and protein metabolismand results from impaired insulin secretion, insulin resistance, ora combination of both." (PMID 36201615, 2022). "Moreover, the HFLowCS can be a useful food item for patients with type 2 diabetes as in the same portion size with simple and whole-grain spaghetti, they take 65% and 30% less carbohydrates, resulting in a better glycemic response and lower need for insulin secretion." (PMID 35270698, 2022). "UCP2 expression is increased in type 2 diabetes mellitus (T2DM), where it inhibits insulin secretion from pancreatic β-cells." (PMID 35629388, 2022). "Patients with type 2 diabetes underwent CGM before and after switching from a twice-daily pre-mixed insulin treatment regimen to a GLP-1 RA (liraglutide) plus basal insulin regimen." (PMID 36463197, 2022). "Insulin and its pharmaceutical formulations have saved the lives of type I diabetic Mellitus (T1DM) and type II diabetic Mellitus (T1DM) patients since its discovery in 19221–3." (PMID 35705561, 2022). "Indeed, HIIT-protocols with shorter training durations have shown the same or better effects on measures of insulin sensitivity, glucose metabolism, VO2max, and body composition compared with endurance training not only in healthy, lean individuals, but also in obesity and type 2 diabetes." (PMID 36387850, 2022). "In studies of humans with type 2 diabetes, glycaemic control is generally better with tirzepatide than with selective GLP-1 RAs (dulaglutide, semaglutide) coincident with a greater insulin response to glucose." (PMID 36050763, 2022). "During the β-cell mass expansion phase of the type 2 diabetes development, the first GSIS phase is often missing, whereas the second phase is enhanced and prolonged, so higher time-integrated insulin release exists." (PMID 34180254, 2022). "Type 2 diabetes mellitus (T2DM) is a medical condition that arises due to an elevated level of blood sugar (glucose) that is caused by the body not being able to produce enough insulin." (PMID 36144852, 2022). "Therefore, they were introduced during the 1990s as insulin-sensitizing glucose-lowering drugs for the treatment of type 2 diabetes mellitus (T2DM)." (PMID 36297575, 2022). "In type 2 diabetes patients, PPAR-γ activation lead to a significant improvement in insulin and glucose indices, owing to an increase in whole body insulin sensitivity." (PMID 36552644, 2022). "Recent studies have shown that DEHP is able to interfere with the insulin signal suggesting DEHP exposure impairs insulin signal transduction and alters glucoregulatory events leading to the development of type 2 diabetes in F1 male offspring." (PMID 35208241, 2022). "In conclusion, the results of this study indicated that eight weeks of supplementation with EA, 180 mg/day, reduced the levels of blood sugar, Insulin, IR, and Fetuin-A and increased SIRT1 in patients with type 2 diabetes." (PMID 33546744, 2021). "High fasting glucose and insulin levels and high HOMA-IR index didn’t only confirm effective induction of experimental type 2 diabetes but also made it possible to observe CNS dysfunction widely described in the literature." (PMID 33918576, 2021). "It should be noted that the highest rates of glycemic profile parameters (HbA1c) and IR (level of insulin and HOMA-IR) were established in type 2 diabetic patients with comorbid obesity and CP." (PMID 35221617, 2021). "We observed a high correlation between BW of type 2 diabetic rats and FBG, TG, LDL-C, leptin, insulin, and TNF-α." (PMID 34039404, 2021). "A total of 5 patients had type 2 diabetes (2 treated only with oral agents, 2 with oral agents and GLP-1 analogues, and 1 with oral agents and insulin); metabolic control was acceptable (glycosylated hemoglobin < 7%)." (PMID 32720093, 2021).
type 2 diabetes (continued). "Activation of the GLP-1R augments glucose-stimulated insulin secretion, and GLP-1 mimetics and dipeptidyl peptidase-4 inhibitors (which block degradation of GLP-1) are used in the treatment of type 2 diabetes." (PMID 33784857, 2021). "Regarding the molecular mechanisms of ER stress and insulin dysfunction, the activation of JNK and the expression of tribble-like protein 3 via IRE1 and PERK have been gaining attention in type II diabetes and obesity." (PMID 34299638, 2021). "Type II diabetes mellitus (T2DM) is a metabolic disorder that occurs in the body because of decreased insulin activity and/or insulin secretion." (PMID 34682532, 2021). "Type 2 diabetes (T2D) is caused by a lack of insulin sensitivity in hepatic and peripheral tissues, combined with loss of insulin secretion due to decreased beta cell function and/or mass." (PMID 34203703, 2021). "One subgroup received pulsatile insulin (PII), one received a continuous insulin infusion while the last had reduced amplitude pulsatile insulin as seen in Type 2 diabetes." (PMID 34458216, 2021). "In both the type 2 diabetes and metabolic syndrome models, treatment with the CCL4 antibody increased pancreatic insulin expression, and reduced circulating insulin, TNF-α, and IL-6 levels." (PMID 33968046, 2021). "This study is aimed at investigating whether dapagliflozin adjunct to insulin therapy further improves glycemic control compared to insulin therapy alone in patients with newly diagnosed type 2 diabetes (T2D)." (PMID 34497852, 2021). "In obese people with type 2 diabetes stratified by CNR1 genotypes (GA and AA genotypes vs GG genotypes), glucose, HbA1c, insulin sensitivity, BMI, body weight, waist circumference and fat mass were measured before and after 14 weeks of liraglutide treatment." (PMID 33594477, 2021). "The type 2 diabetes was discovered at 25 years old and rapidly treated with metformin, glinid, GLP-1 analogue, and insulin." (PMID 35011612, 2021). "Type 2 diabetes mellitus (T2DM) is a worldwide chronic metabolic disease that occurs when pancreatic β-cell function is impaired and insulin cannot be produced, leading to hyperglycemia." (PMID 34750480, 2021). "Consistent with prior studies of potential insulin glargine biosimilars, INSTRIDE 1 and INSTRIDE 2 were structured to assess immunogenicity of type 1 and type 2 diabetes patient populations independently." (PMID 34174848, 2021). "Among these AMPK-restoring agents is metformin, a hypoglycemic drug used to treat patients with type 2 diabetes, which is known to trigger the AMPK pathway in insulin-sensitive organs, such as the heart." (PMID 33547494, 2021). "Two patients had type 2 diabetes (1 treated with oral agents, GLP-1 analogues, and insulin, and the other with oral agents and insulin); metabolic control was acceptable (glycosylated hemoglobin < 7%)." (PMID 32720093, 2021). "To identify the pathological stages of type 2 diabetes in OLETF rats, we measured body weight, food intake, blood glucose, and plasma insulin levels." (PMID 34506507, 2021). "Type 2 diabetes mellitus (T2DM) is a complex disease characterized by insulin resistance in peripheral tissues and dysregulated insulin secretion by pancreatic β-cells." (PMID 35069684, 2021). "Type 2 diabetes mellitus (T2DM) is an energy metabolic disorder characterised by high blood glucose and reduced insulin secretion, a pathogenesis closely related to insulin resistance and impaired islet β cell function." (PMID 34688315, 2021). "This could mean that a genetic predisposition to lower insulin sensitivity results in a lower birthweight but, in keeping with the monogenic and epidemiological data, the different pathways affecting insulin action are not consistently shared between birthweight and type 2 diabetes risk." (PMID 33569631, 2021). "Type 2 diabetes mellitus (T2DM) is a metabolic disorder characterized by chronic hyperglycemia, insufficient insulin secretion or action, or insulin resistance (IR)." (PMID 34257694, 2021).